TLR4 (toll like receptor 4)
Diseases named in the same sentence as TLR4 in open-access papers (continued):
Sharing a sentence is not in itself a finding about the gene and the disease.
hepatocellular carcinoma (continued). "The hypothesis of this study was whether miR-122 plays a role in inflammatory pathways through regulating TLR4 expression in hepatoma cells." (PMID 31340754, 2019). "The upregulation of miR-122 could regulate host innate immunity by TLR4 in hepatoma cells, which will provide a strategy for cancer treatment." (PMID 31340754, 2019). "Additionally, TGFβ-mediated signaling plays a critical role in GO-mediated biological/toxicological effects on human hepatoma HepG2 cells, whereas rGO regulates immune responses via the TLR4-NFκB pathway." (PMID 29973666, 2018). "Recent studies suggest that activation of TLR4 with ligand LPS may promote hepatocellular carcinoma (HCC) by increasing proliferative signals in resident liver cells and the liver." (PMID 29085012, 2017). "Furthermore, over expression of TLR4 on hepatocellular carcinoma cells was positively correlated with the number of CD4+CD25highFOXP3+ Treg in tumor tissue, which leads to immune tolerance and tumor progression." (PMID 29029545, 2017). "In addition, we detected TLR4 expression of the hepatocellular carcinoma cell line MHCC97-H cells which had been confirmed with a strong ability to metastasize." (PMID 22938142, 2012). "In hepatocellular carcinoma (HCC), M2-polarized tumor-associated macrophages (TAMs) promote EMT and cancer cell migration via the TLR-4/STAT3 signaling pathway." (PMID 40404908, 2025). "APs may modulate immunity by activating the toll-like receptor 4 (TLR4)–mediated myeloid differentiation primary response 88 (MyD88)–dependent signaling pathway and induce apoptosis in human hepatocellular carcinoma cells by decreasing the expression of Notch1." (PMID 38466979, 2024). "However, the role of TLR4/PERK/CHOP signaling in the 5-FU resistance of hepatocellular carcinoma remains unclear and requires further exploration." (PMID 37304412, 2022). "One of these studies suggested that TLR4 induces autophagy and performs a protective function against the progression of hepatocellular carcinoma (HCC)." (PMID 34575052, 2021). "Thus, the TLR4–NF-κB pathway might be an important signal pathway, and might participate in LPS-induced cytokine increase and cell proliferation in hepatoma cells." (PMID 30678222, 2019). "Intestinal microbiota and TLR4 signaling also have potential roles in promoting hepatocellular carcinoma (HCC) proliferation." (PMID 31225446, 2017). "However, there has not been any investigation about TLR4 polymorphisms in hepatocellular carcinoma yet." (PMID 21559380, 2011). "Recent studies have demonstrated that the gut pathobiont Klebsiella pneumoniae(K. pneumoniae), enriched in liver tissue, interacts with TLR4 on hepatocellular carcinoma (HCC) cells via its surface protein PBP1B, activating the TLR4-mediated oncogenic signaling pathway to promote tumor progression." (PMID 40589752, 2025). "As a ligand for TLR2 and TLR4, extracellular HSPA1A potently stimulates proliferation and inhibits apoptosis in hepatocellular carcinoma cells via TLR2 and TLR4 signaling pathway and activation of nuclear factor-κB (NF-κB)." (PMID 38646439, 2024). "For instance, FSTL1 can bind to TLR4, activating AKT/mTOR/4EBP1 signaling and enhancing hepatocellular carcinoma metastasis and stemness." (PMID 38605354, 2024). "In hepatocellular carcinoma (HCC), M2 macrophages promote HCC cell migration and EMT via the TLR4/STAT3 signaling pathway." (PMID 38213716, 2024). "In hepatocellular carcinoma (HCC), the activation of TLR4 and TLR9 by NETs led to upregulation of cyclooxygenase-2 (COX2), which enhanced the invasiveness of tumor cells." (PMID 37958984, 2023). "Actually, the activation of TLR2 and TLR4-mediated innate immune response can inhibit HBV and WHV replication in hepatoma cells and woodchuck hepatocytes, respectively." (PMID 36298831, 2022). "In hepatocellular carcinoma (HCC), TLR4 and intestinal microbiota were required for tumour promotion and this was mediated by resident liver cells." (PMID 32745353, 2020).
hepatocellular carcinoma (continued). "Toll-like receptor 4 expression on CSCs of hepatocellular carcinoma (HCC) was reported." (PMID 30841635, 2019). "Here, we find that the expression of TLR4 in relapsed human hepatocellular carcinoma (HCC) clinical samples is higher than that in the non‐relapsed ones, which leads us to explore the role of TLR4 in cancer stemness." (PMID 30957973, 2019). "The reciprocal regulation of tumor-initiating stem-like cells by TLR4, and TGF-β requires YAP1 and IGF2BP3 in hepatocellular carcinoma (HCC)." (PMID 29312609, 2017). "Similar to human hepatoma cells, the expression of wPD-L1 was upregulated by TLR3 (14.9-fold) and TLR4 (4.3-fold) ligands, woodchuck IFN-α (4.3-fold) and -γ (4.6-fold) in PWHs." (PMID 22022563, 2011). "Downstream of TLR4 and MyD88, activated NF-κB can bind the SAA3 promoter and has been shown to regulate SAA3 transcription in hepatoma-derived cell lines and mouse adipocytes." (PMID 19513118, 2009). "Through the use of specific inhibitors and gene knockdown experiments, we were able to show that the two processes essential for the induction of hepatoma cell death by GGA [XI] are UPRER induction and TLR4 activation, which are suppressed by cotreatment with OA as in the case of PA." (PMID 37247782, 2023). "For example, NANOG is induced by toll-like receptor 4 (TLR4) signaling via the phosphorylation of E2F1, and the downregulation of NANOG slows down hepatocellular carcinoma (HCC) progression induced by alcohol, a Western diet, and hepatitis C virus protein in mice." (PMID 36833320, 2023). "Additionally, TLR4 and LY96, which are genes in the TLR signaling pathway that promote cell survival and proliferation in hepatocellular carcinoma, were significantly downregulated in shTREM1 HepG2 tumors." (PMID 37651197, 2023). "HBX can interact with TLR4 in HBV-related hepatoma cells, and the physical interaction of HBX with TLR4 may contribute to the activation of ERK1/2 in hepatoma cells." (PMID 35251017, 2022). "Similarly, neutrophils have been shown to induce hepatocellular carcinoma (HCC) metastasis by releasing NETs that, once internalized by HCC cells, activate the TLR4 and subsequently induce cell-death resistance and enhanced invasiveness." (PMID 35664746, 2022). "Based on these studies, we hypothesised that GGA stimulates TLR4 signalling to induce UPR, activates CASP1, and then induces pyroptotic cell death in human hepatoma cells." (PMID 32270855, 2020). "Many studies showed the evidence for the pathogenic role of TLR4/LPS signaling in the progression of alcoholic and nonalcoholic fatty liver diseases [ALD, non-alcoholic fatty liver disease (NAFLD)] and hepatocellular carcinoma." (PMID 30022981, 2018). "However, the effects of TLR4 on M2-polarized macrophages in hepatocellular carcinoma (HCC) are unknown." (PMID 29338742, 2018). "In HepG2 hepatocellular carcinoma cells, TGFβ has been reported to increase mRNA levels for BAMBI, whereas endotoxin (LPS) downregulated mRNA for BAMBI in murine hepatic stellate cells via TLR4." (PMID 20886049, 2010). "In hepatocellular carcinoma (HCC), LPS promotes cell survival, proliferation, invasion, and production of pro-inflammatory mediators, including TNF-α, iNOS, IL-1β, IL-6, CCL-2, CCL-22, vimentin, and epidermal growth factor receptor (EGFR), through the induction of TLR4 signaling." (PMID 40444051, 2025). "Other TLR4 antagonists like paeonol (PAE) and CXC195 have shown promises as potential anti-cancer drugs that function through regulating the activation of the TLR4-MAPK/NF-κB pathway in human osteosarcoma as well as hepatocellular carcinoma as derived from their efficacy in cell culture experiments." (PMID 37822929, 2023). "Since interleukin-1 receptor and TLR4 signaling triggers MYD88 innate immune signal transduction adaptor (MyD88) activation cascade in monocytes, the effect of levantinib could be not only on hepatoma cells, but also on monocytes." (PMID 32397371, 2020).
hepatocellular carcinoma (continued). "Furthermore, TLR3/TLR4-TRIF exerts a crucial antiviral role in the initial stage of viral hepatitis, and when viral hepatitis progresses to serious complications such as cirrhosis and hepatocellular carcinoma, TLR3/TLR4-TRIF has been found to accelerate the disease process." (PMID 38694821, 2024). "The researchers incorporated lipopolysaccharide (LPS), a key component of Gram-negative bacteria and potent TLR4 activator known to modulate the tumor immune microenvironment, in their investigation of USP8-mediated hepatocellular carcinoma regulation." (PMID 40607251, 2025). "Furthermore, In hepatocellular carcinoma, CXCL10/TLR4-mediated MMP14 activation promotes recruitment of monocytic myeloid-derived suppressor cells (MDSCs) after acute liver injury, fueling post-transplant HCC relapse, as evidenced by clinical data, animal studies, and cell-culture assays." (PMID 41404065, 2025).
injury (130 papers, 2008 to 2026). Damage inflicted on the body as the direct or indirect result of an external force, with or without disruption of structural continuity. "In conclusion, brain Prx2 levels are elevated as red blood cell lysis increases after autologous arterial blood injection and increased Prx2 levels can cause inflammatory brain injury through the TLR4 pathway." (PMID 38516845, 2024). "Toll-like receptor-4 (TLR-4) is essential to innate immune responses and has been implicated in the pathobiology of acute inflammatory lung injury." (PMID 28261612, 2017). "Recent work has shown TLR4-dependent synapse loss after traumatic brain injury, which could be reduced by TLR4 blockade." (PMID 36309735, 2022). "For example, the TLR4 rs10116253-2242C allele enhances the transcriptional activities and expression of TLR4, and trauma patients with the variant C allele have a greater capacity to produce the pro-inflammatory cytokines TNF-α and IL-6 than those with other alleles." (PMID 30683156, 2019). "TLR4 has been linked with TBI where TLR4 mediates glial phagocytic activity and inflammatory cytokines production and plays an important role in inflammatory response and brain injury." (PMID 30271319, 2018). "Because microglial TLR4 is linked to inflammation and pain, its high expression at late time-points supports the idea that hSOD1G93A microglia adopt an exacerbated "pain-related" activation state after nerve injury." (PMID 21489258, 2011). "CRAMP administration mediated exacerbated mouse heart injury might be associated with enhancing TLR4 and P2X7R/NLRP3 signaling, since CRAMP administration mediated detrimental effects could be entirely reversed by inhibition of TLR4, P2X7R, and NLRP3 inflammasome." (PMID 35410418, 2022). "In D-GalN-induced acute liver injury, the TLR4/MyD88/NF-κB signaling pathway plays a pivotal role by regulating inflammatory responses and apoptosis, thereby influencing the severity of liver injury and the repair process." (PMID 41465230, 2025). "This is supported by previous findings showing that S100A8 triggers IL-6 and MCP-1 production and neutrophil recruitment through TLR4 activation in alveolar epithelial cells, exacerbating inflammation in models of acute lung injury." (PMID 40723384, 2025). "HT also modulated macrophage polarization and inhibited the TLR4/NF-κB pathway, demonstrating its anti-inflammatory and antioxidant properties in acute liver injury." (PMID 39334699, 2024). "Utilizing genetically modified mouse models, studies have revealed the critical roles of Notch, Ras, and toll-like receptor 4 (TLR4) signaling pathways in hyperoxia-induced neonatal brain injury." (PMID 39768185, 2024). "In synthesis, the interdependent roles of TLR4 and NF-κB form the crux of alcohol-inflicted hepatic trauma." (PMID 37868808, 2023). "Concurrently, the negative regulatory effect of MUC1 on the TLR4/MyD88/NF-κB pathway has been described in other diseases, such as acute lung injury and acute kidney injury." (PMID 37880668, 2023). "High-mobility group box1 (HMGB1), a key regulator of acute lung injury (ALI), is known to mediate the activation of the TLR4 (toll-like receptor 4)/NF-κB pathway; moreover, the block of this pathway has been shown to relieve LPS-induced acute lung injury." (PMID 37892993, 2023). "Consistently, the constructing PPI network in our result provides evidence that MAPK14 (p38α) activation was shown to make greater contributions to TLR4-mediated MMP-9-induced post-aSAH brain injury." (PMID 36438795, 2022). "Recent study reveals that GLY inhibits the activation of HMGB1/TLR4/NFκb signal pathway in radiation-induced acute lung injury." (PMID 35586052, 2022). "Hypothermia inhibits microglial cells activation by modulating autophagy/apoptosis and the MyD88-dependent TLR4 signaling pathway after traumatic brain injury." (PMID 35873794, 2022).
injury (continued). "The microglial activation through the Toll-like receptor (TLR)-4 signaling pathway has been reported to play an essential role in ICH-induced brain injury." (PMID 34067678, 2021). "Increased levels of circulating and intrapulmonary endotoxin after combined injury prompted us to pursue potential role of the intracellular endotoxin receptor caspase-11 (TLR4-independent) in acute lung injury." (PMID 34349759, 2021). "Evidence suggested that LPS-toll-like receptor 4 signaling potentiates IL-1β release and subsequently upregulates IL-1RI expression on the surface of macrophages in acute lung injury model." (PMID 33081813, 2020). "Previous studies have demonstrated that WISP1 interacted with TLR4 and contributed to ventilator-induced lung injury (VILI) dependent on TLR4 signaling." (PMID 30522479, 2018). "Another molecular player which has been described as a crucial component in the pathologic process leading to neuronal death and neurodegeneration following traumatic brain injury is Toll-like receptor 4 (TLR4)." (PMID 29438357, 2018). "Increased TLR4 expression correlates with the development of pain after nerve injury and its inhibition significantly attenuates nerve injury-induced pain." (PMID 28270702, 2017). "In this context, signaling of HA fragments via TLR2 and TLR4 was shown to regulate the inflammatory response to BLM-induced lung injury and promote recovery and repair, at least in the acute BLM model." (PMID 28836991, 2017). "High expression of TLR4 and down streaming molecules such as MyD88 play an essential role in progression of LPS induced acute liver injury and act as powerful mediator of inflammatory process and innate immune activation." (PMID 28241791, 2017). "Nonetheless, a recent study in a rat model of traumatic brain injury demonstrated that resatorvid administration prior to the injury significantly reduced the expression of TLR-4 at 12, 24, and 48 h following traumatic brain injury." (PMID 29113143, 2017). "Our study supports a molecular mechanism by which disruption of PTEN/Foxo1 signaling regulates TLR4-mediated innate immunity, a novel approach for the management of innate immunity-driven lung injury." (PMID 25759027, 2015). "In the present study, the effect of TLR4 monoclonal antibody (mAb) on LPS-induced acute lung injury (ALI) was investigated in mice." (PMID 25120616, 2014). "It is also known that cells from trauma patients secrete significantly less inflammatory cytokines than cells from control subjects when LPS, a TLR4 agonist, is used." (PMID 21184675, 2010). "In the LPS model of acute lung injury, TLR4 mut or TLR4−/− mice were, as expected, highly protected from the development of tissue damage in the LPS-induced model of acute lung injury." (PMID 19503602, 2009). "Recent studies have illustrated that the interaction of Toll-like receptor 4 (TLR4) with hypoxia-inducible factor-1α (HIF-1α) in alveolar macrophages (AMps) plays a key role in initiating inflammatory responses during acute lung injury/reperfusion (ALI/R)." (PMID 39682819, 2024). "Some previous studies have found that the expression of miR-27a in LPS-induced RAW264.7 macrophages was downregulation, and overexpression of miR-27a alleviated LPS-induced acute lung injury in mice via inhibiting inflammation and apoptosis through modulating TLR4/MyD88/NF-κB pathway." (PMID 38105216, 2023). "ERK and TLR4 signaling pathways can activate related proteins, leading to the activation of inflammatory factors such as IL-1 and IL-6, with the end result of liver injury." (PMID 37894611, 2023). "Therefore, our studies’ overexpression of TLR2 and TLR4 and oxidative stress synergistically progresses acute lung injury induced by acute kidney injury." (PMID 35911649, 2022). "Folic acid could reduce the intestinal leakage of LPS and inhibit the activation of the LPS/TLR4/NF-κB signaling pathway, which demonstrated that folic acid could exert anti-inflammatory effects to ameliorate alcohol-induced liver injury." (PMID 36337656, 2022).